RNU1-117P (RNA, U1 small nuclear 117, pseudogene)
Gene: Small nuclear RNA gene on chromosome 12 (88,581,639 to 88,581,796, forward strand). Ensembl gene ENSG00000252850.
Homologues: Orthologues: chimpanzee U1 (100% identical), macaque U1 (90% identical). Paralogues in human: RNVU1-28 (74% identical), RNU1-1 (73% identical), RNU1-2 (73% identical), RNU1-27P (73% identical), RNU1-28P (73% identical), RNU1-3 (73% identical), RNU1-4 (73% identical), RNVU1-18 (73% identical), RNVU1-29 (73% identical), U1 (73% identical), RNVU1-27 (73% identical), RNVU1-7 (73% identical), and 134 more.